FOXP3 (forkhead box P3)
Diseases named in the same sentence as FOXP3 in open-access papers (continued):
Sharing a sentence is not in itself a finding about the gene and the disease.
cancer (continued). "Some of the discord in whether or not Treg cells in cancer are associated with poor outcome has been attributed to the pitfalls of relying on CD25 and Foxp3 for Treg cell identification, given that effector T (Teff) cells transiently express both markers upon activation." (PMID 28033393, 2016). "Besides the integration of CD25low/− FOXP3-expressing Treg cells, analysis of CD127 might, furthermore, clarify contradictory results concerning frequencies as well as prognostic value of Treg cells in cancer patients." (PMID 21904560, 2011). "FOXP3 expression does not equate strictly to Treg identity and has also been described in CD4+CD25−T cells, and cancer cells." (PMID 38077395, 2023). "In two studies of RT, patients with squamous cell skin cancer have higher CD4+CD25+Treg than those without cancer, and have lower T cell counts and lower CD8/Foxp3 ratios." (PMID 36426347, 2022). "In this latter study, RT patients without a history of cancer post-transplant had similar numbers of Treg to HV, whereas patients with cancer post-transplant had increased CD4+CD25+Foxp3+Treg." (PMID 36426347, 2022). "Serum SOCS1, TAB2, and Foxp3 level in cachectic and non-cachectic pancreatic and NSCL cancer patients and cachexia severity." (PMID 34900737, 2021). "TGF-β and adenosine, released from cancer cells and also MDSCs, seem to play a key role in generating suppressive CD25+ FoxP3+ Tregs from non-suppressive CD25− FoxP3− conventional Tregs." (PMID 34025641, 2021). "Immune histology of residual RT2-cancers showed CD3+ cells, MHC class II+ and F4/80+ cells following ICB/AT treatment but only very few or no Foxp3+ regulatory T cells, CD8+ or CD49b+ cells." (PMID 32165639, 2020). "Tumoral PD-L1(+) alone was an adverse prognostic factor in EBV-positive carcinomas, but not in MSI-high carcinomas, whereas PD-L1(+) immune cells or FOXP3+/high TILs alone were correlated with a favorable prognosis." (PMID 32498695, 2020). "In the specimens, the median and interquartile range of the percentage of Foxp3+ cells among CD3+ cells were 17.1% (11.9, 11.4–23.3%), while those in the control group without cancer were 2.6% (4.9, 1.1–6.0%) (P < 0.001)." (PMID 30261082, 2018). "Comparing levels of different Treg subpopulations in cancer patients and controls, we report that in PC patients, and unlike LICRC patients, there was no increase in Treg levels as defined by FoxP3 and Helios." (PMID 26885615, 2016). "The majority of Tim-3+ CD4 T cells in the peritumoral stroma did not express Foxp3, whereas most Tim-3+ CD4 T cells in the cancer nest co-stained brightly with Foxp3." (PMID 23526963, 2013). "In contrast, the majority of Tim-3+ CD4 T cells isolated from the peripheral blood of healthy donors and cancer patients did not express the Treg-related molecules CD25 and Foxp3." (PMID 23526963, 2013). "In vitro, lenalidomide inhibited Treg proliferation and diminished FoxP3 expression in the absence of measurable effects on TGF-β or IL-10 production, while reducing Treg cell accumulation in lymph nodes of CT26 cancer-bearing animals." (PMID 22567028, 2012). "IL-30-silenced tumors developed in IL-30KO mice, IL-30−/−tumors, lacked vascular supply and displayed frequent apoptotic cancer cells entrapped by perforin+TRAIL+CD3+Tlymphocytes, most of which had a CD4+T phenotype, whereas IL-10+TGFβ+Foxp3+Tregs were lacking." (PMID 31366386, 2019). "Although no statistical difference for expression of IL-4, IL-17 and Foxp3 mRNA levels in carcinoma tissues of non-IBC and IBC patients was observed, there was a trend for upregulation of IL-4 and downregulation of Foxp3 mRNA levels in carcinoma tissues of IBC in comparison to non-IBC." (PMID 31145753, 2019). "Lack of significant correlations between number of Foxp3+ and CD8+ cells in both studied groups of cancers suggest that CD8+ cells observed in our study may have other than regulatory functions or represent non-traditional subpopulation of Tregs." (PMID 28669079, 2018).
cancer (continued). "We also assessed residual cancer burden (RCB) scores on surgical specimens of non-pCR patients by using the Web-based MD Anderson RCB calculator and its relationship with CD8+ TIL, FOXP3+ TIL, and CD8/FOXP3 ratio." (PMID 26341640, 2015). "Taken together, these data suggest that circulating LAP-positive CD4+ Foxp3+ Tregs, rather than the general population of CD4+Foxp3+ T cells, can be used as a more accurate and specific marker for monitoring the immunological status of cancer patients." (PMID 25268580, 2014). "Although Nrp1+ CD4+ T cells may co-express CD25 and exert regulatory function in some cancer-draining lymph nodes, in non-malignant lymph nodes and tonsils, Nrp1+ CD4+ T cells have a non-regulatory (CD25- FoxP3-) memory (CD45RA- CD45RO+) phenotype." (PMID 24386482, 2013). "The experience accumulated in the field of cancer therapy with immune checkpoint inhibitors provides evidence that the microbiota govern the balance between CD8+ T cell activation and inflammation on one side and CD4+/FoxP3+ T reg cells and lack of inflammation on the other side." (PMID 32793150, 2020). "Interestingly, FOXP3+ T lymphocyte infiltration was significantly correlated with CD73 protein levels in the stroma but not in the epithelium of LumA and TN BC, suggesting that CD73-mediated immunosuppression is exerted through CD73 expression in CAF rather than in cancer cells." (PMID 34884993, 2021).
infection (550 papers, 2004 to 2026). The state of being infected such as from the introduction of a foreign agent such as serum, vaccine, antigenic substance or organism. "During the initial and the chronic phase of the infection, F. hepatica is associated with the expansion or recruitment of Foxp3 (the forkhead box transcription factor, a type of Treg cells) and the induction of adaptive Ag-specific Treg cells." (PMID 40864127, 2025). "An increased accumulation of immune-dysfunction-associated CD4+Foxp3+ regulatory T cells (Tregs) is observed in aging oral mucosa during infection." (PMID 33968777, 2021). "CD4+Foxp3+Tregs maintain immune homeostasis, but distinct mechanisms underlying their functional heterogeneity during infections are driven by specific cytokine milieu." (PMID 33240286, 2020). "This culture yielded CD8+CD25+FoxP3+ Treg lymphocytes that were able to inhibit the allogeneic immune response without affecting the one against the cytomegalovirus, a risk of infection among patients transplanted with hematopoietic stem cells." (PMID 30155493, 2018). "When assayed 24 hours post-operatively, lower mRNA levels of TNFα (P = 0.03), IL-12 (P = 0.02), T bet (P = 0.04), IL-23 (P = 0.02), RORγt (P = 0.05) and FOXP3 (P = 0.02) were also associated with the subsequent development of an infection." (PMID 30212506, 2018). "Both Th2 and ex-Foxp3 Th2 cells were able to passively transfer immunity to normally susceptible Hp 1° hosts, resulting in a significant reduction in the establishment of infection, compared with mice receiving naive CD4+ T cells." (PMID 28507062, 2017). "Unexpectedly, the number of classical CD4+Foxp3+ Tregs producing IL-10 was similar in the cardiac tissue of Ebi3-deficient and WT mice at day 15 after infection, suggesting that Ebi3 was unable to promote the development of classical Tregs." (PMID 29033934, 2017). "In contrast, the expansion of CD4+CD25+Foxp3+ regulatory T cells (Tregs) and excessive release of proinflammatory cytokines during infection enhance host susceptibility to infection." (PMID 28769924, 2017). "Expansion of Foxp3+CD4 T cells with regulatory function (T-reg) associated with infections and malignancies have been shown to be primarily due to T cell immune responses to microbial or tumor antigens." (PMID 27441095, 2016). "A putative and somewhat contradictory role of CD4+Foxp3+ Tregs has been demonstrated in various models of pathogenic infections." (PMID 27439902, 2016). "For example, Wei and Tabel showed that depletion of CD4+CD25+Foxp3+ T cells by anti-CD25 mAb leads to complete control of infection in highly susceptible BALB/c mice." (PMID 27242788, 2016). "There were clear changes associated with long-term infection including a reduction in % FoxP3± regulatory CD4± T cells within the lamina propria and % T-bet± Th1 cells in the epithelium." (PMID 25938477, 2015). "We use experimental infection of mice with the pathogenic nematode Strongyloides ratti to investigate the role of Foxp3+ Treg during helminth infection." (PMID 24516385, 2014). "Accordingly, parasites co-inoculated with saliva (SGE-1X) caused an increase in the recruitment of CD4+Foxp3+ cells to the infection site, suggesting that saliva of L. longipalpis increases Tregs during the infection." (PMID 23656976, 2013). "Increased expression of IFNγ, IL-10, and FOXP3 has been associated with longer episodes of infection." (PMID 23457650, 2013). "Although H3 infected mice normally have few CD4+CD25+FoxP3+ cells, H3 infection of γδ cell deficient mice results in significant increases in Treg cells and suppression of myocarditis." (PMID 21255407, 2011). "Enhanced IFNγ-responses by C. pneumoniae-specific CD4+ T-cells in TLR2/4 double-deficient mice are best explained by an impaired infection-associated expansion of CD4+CD25+Foxp3+ regulatory T-cells." (PMID 22096480, 2011).
infection (continued). "Consistent with the published data, in our hands DEREG mice depleted of Foxp3+ cells the day prior to, and over the course of infection, remained as susceptible to ECM as Foxp3+ cell replete DEREG mice (data not shown)." (PMID 21170302, 2010). "In the CL model by L. braziliensis, we observed an anti‐inflammatory effect, potentially caused by the significant increase in CD4+LAP+ and CD4+CD25+Foxp3+ T cell frequencies in draining lymph nodes from 6 to 8 weeks post‐infection in mice from Lb/HSP65 compared to Lb and Lb/Ø groups." (PMID 40745935, 2026). "Indeed, L-Kyn treatment induced a robust increase in pulmonary Treg (CD4+CD25+Foxp3+) cells, and this finding was associated with the large expression of mRNA for Foxp3 in the two periods of infection studied." (PMID 33936043, 2021). "Hence, this suggests the transdifferentiation of Th17 cells into Th17-specific Treg17 and the induction of FOXP3+ Treg at epithelial and mucosal barriers in TL fish enhancing their susceptibility to infection." (PMID 32542025, 2020). "Supporting this tenet, reduced CD25 expression in aged Foxp3+ cells (X-axis, X-axis) and their likely inability to regulate IL-2 is likely associated with their dysfunction and immunopathology during infection in aged mice." (PMID 33240286, 2020). "This could, in part, result from a dominant Th2 differentiation of Foxp3+ Tregs upon loss of Foxp3 expression observed after parasite-driven transient expansion of Foxp3+ Tregs after 7 days of infection in our assay." (PMID 32457746, 2020). "However, populations of CD8+ Treg cells expressing FoxP3 are important immune-suppressors during chronic or asymptomatic infections caused by suboptimal amounts of the infectious agent." (PMID 30155493, 2018). "As reported MTB infection is associated with an increase in the frequency of CD4+CD25+FoxP3+Treg in the blood and at the site of infection, resulting in MTB specific immunity suppression that may foster the chronicity of MTB infection." (PMID 29259310, 2017). "While TGF-β was upregulated at 3 dpi, Foxp3 (Treg transcription factor) was upregulated at a later stage of infection (28 dpi), indicating that Tregs (also known as Foxp3-expressing cells) play a more diverse role than causing early immunosuppression in regulating immune responses." (PMID 29216911, 2017). "A decreasing trend in FoxP3 transcription between infected groups together with increasing parasite density between these groups in the skin also support the notion that FoxP3 might be associated with a protective role in this infection." (PMID 26465878, 2015). "Indeed, decrease numbers of FoxP3+ Treg cells in the lungs of resistant and susceptible mice at both post-infection periods were observed." (PMID 25411790, 2014). "Since IL-10 secretion by CD4+ CD25+ FoxP3+ Treg cells as well as CD4+ CD25− FoxP3− Th1 cells has been implicated in the control of chronic infection with Leishmania, it was important to determine the T cell population secreting IL-10 early after infection." (PMID 23825956, 2013). "However, upon infection TLR2/4 double-deficient mice displayed a lower frequency of CD4+CD25+Foxp3+ regulatory T-cells in vivo and the frequency of regulatory T-cells was inversely related to the frequency of CD4+IFNγ+ T-cells." (PMID 22096480, 2011). "We next determined whether the increase in Treg cell numbers caused by IL-2Jc treatment during infection was the result of natural Treg cell expansion, or de novo conversion of naïve, Foxp3− CD4+ T cells into Treg cells." (PMID 21170302, 2010). "Despite observations that LAG3 deficiency delays lesion growth by inhibiting Foxp3+ Treg and Th2 cell differentiation and promoting Th1 cell formation in the late stage of E. multilocularis infection, our data revealed a different outcome in the middle stage of infection." (PMID 37172058, 2023).
infection (continued). "Therefore, an imbalance in the frequency and number of CD4+Foxp3+ cells, which is associated with the augmentation of Th1 effector cell function, has a deleterious effect on the magnitude of lung inflammation and, consequently, in the infection control." (PMID 30584243, 2018). "Moreover, CD4+Foxp3+ cell-mediated suppression contributes to infection susceptibility." (PMID 30584243, 2018). "However, while CD103 expression levels among uninfected LP Tregs were broadly similar in the two strains, by 7 days following infection CD103 expression within the Foxp3+ compartment was more than twofold higher in the susceptible C57BL/6 mice than in the resistant SJL." (PMID 24492801, 2014). "Therefore, to determine whether ICOS deficiency has a similar impact on Foxp3+ Treg cells at the infection site, we compared Foxp3+ Treg-cell responses in the LP of the small intestine of H. polygyrus-infected WT and ICOS−/− mice." (PMID 23319295, 2013). "In addition, the differences seen in the infection susceptibility of Tregs as compared to FoxP3-expressing cells may also be partly due to presence of non-Treg activated T-cells within the purified cells." (PMID 15252446, 2004). "Natural regulatory T cell levels (CD4+, CD25+, and Foxp3+) are significantly increased in Giardia infection." (PMID 41970608, 2026). "Foxp3+ Tregs accumulate in mouse brains during CM in a time-dependent manner that continuously increases until 35 days post-infection (dpi)." (PMID 40766255, 2025). "Because TREG cells responding to autoimmune inflammation or infection in vivo are exposed to a complex mix of signals, we next sought to define the requirements for Foxp3 in TREG cells responding to defined cytokine stimuli." (PMID 40478934, 2025). "Following electroceutical treatment, anti-infection genes such as Il10ra and Foxp3 were up-regulated, whereas genes promoting immune response and metabolism, including Il17d and Map3k7, were down-regulated." (PMID 39951521, 2025). "This suppression is mediated by infection-induced CD4+Foxp3+ regulatory T cells (Tregs), as their depletion reverses the protective effect, leading to aggravated AAI." (PMID 40432048, 2025). "Increased CD4+CD25+Foxp3+ Tregs have also been documented in the peritoneal cavity of mice intraperitoneally infected with E. multilocularis, and their depletion improved infection control." (PMID 40725240, 2025). "We used qPCR to analyze the expression of Foxp3 in colonic tissue in maternal mice 90 days post-Emu infection." (PMID 40713878, 2025). "Tem cells (CD44+ CD62L−, gated on CD4+ FOXP3+) were increased by MNV infection in Ncf190H mice, whereas naive Tregs (CD44− CD62L+, gated on CD4+ FOXP3+) and Tcm/ Tvm cells (CD62L+ CD44+, gated on CD4+ FOXP3+) were decreased." (PMID 39939342, 2025). "In this regard, an enhanced expression of TGF-β1 and Foxp3 was detected in the brain of CLEC12A−/− mice following TMEV infection." (PMID 41214106, 2025). "QRT-PCR analysis revealed that, relative to the Pm-infected group, the expression levels of IFN-γ, IL-4, IL-6, IL-17, TGF-β, GATA-3, T-bet, RORγt, and FoxP3 genes were significantly elevated in the Pm_OMVs-infected group at 24 hours post-infection (P < 0.01)." (PMID 41306977, 2025). "Foxp3-DTR neonates or adults were treated every other day with diphtheria toxin (DT) following either HMPV or mock infection." (PMID 40280180, 2025). "Concerning the histological distribution, CD4+, GZMB+ and Foxp3+ cell counts were higher at the IF region compared to the GC (p˂0.0001) considering the whole cohort and each infection status analyzed separately (p˂0.05)." (PMID 38273012, 2024). "In accord, we observed increased Il-10, Cd4, Cd8a, and Foxp3 mRNAs in our RNA-seq data from K-RasLA1 mice on day 7 post-infection." (PMID 39338937, 2024). "The frequencies (in %) of CD4+ T cells, CD8+ T cells, and CD4+/CD25+FoxP3+ regulatory T cells (Tregs) in the lung and thymus were determined on day 3, 6 and 9 post infection." (PMID 38979428, 2024).